FGFR1 (fibroblast growth factor receptor 1)
Diseases named in the same sentence as FGFR1 in open-access papers (continued):
Sharing a sentence is not in itself a finding about the gene and the disease.
gastric cancer (47 papers, 2014 to 2025). A primary or metastatic malignant neoplasm involving the stomach. "Anyhow, the high expression of FGFR1 in gastric cancer was tightly associated with the poor survival rate of patients with gastric cancer." (PMID 33041789, 2020). "In our present study, FGFR1 was up-regulated in gastric cancer tissues and cell lines and associated with poor survival prognosis, metastasis, and TNM stage, suggesting that FGFR1 played a crucial role in the carcinogenesis of gastric cancer." (PMID 30484492, 2018). "FGFR1 was frequently up-regulated in gastric cancer tissues and associated with poor overall survival in patients with gastric cancer." (PMID 30484492, 2018). "FGFR1 is implicated in the carcinogenesis of gastric cancer, and FGFR1 inhibitor, L16H50, and L6123 can suppress cell proliferation and migration in gastric cancer cells." (PMID 30484492, 2018). "Treatment of macrophages and gastric cancer cells with recombinant IGFBP7 further showed that IGFBP7 promoted tissue-associated macrophages (TAM)/M2 polarization via FGF-2/Fibroblast Growth Factor Receptor 1 (FGFR-1)/Phosphoinositide 3-kinases (PI3K)/Protein kinase B (Akt) axis." (PMID 39045455, 2024). "FGFR1 is also implicated in a higher risk of distant metastasis and chemo-resistance of various cancer, such as malignant lymphoma, breast cancer, and gastric cancer." (PMID 33041789, 2020). "In addition, the association between FGFR1 mRNA expression and overall survival prognosis was evaluated by the Kaplan-Meier survival curve in patients with gastric cancer." (PMID 30484492, 2018). "However, the underlying molecular mechanism of miR-497 in gastric cancer progression by targeting FGFR1 is rarely investigated." (PMID 30484492, 2018). "In gastric cancer, FGFR1 expression correlates positively with CD8+, CD4+, and dendritic cell infiltration, whereas FGFR4 expression shows a negative correlation with lymphocyte infiltration." (PMID 41514604, 2025). "For instance, FGFR1 amplifications were notably prevalent in breast and lung cancer, while FGFR2 mutations were frequently in endometrial and gastric cancers (GCs)." (PMID 39138146, 2024). "The study noted that FGFR1-4 aberrations occurred in 12.2% of the gastric cancer samples with amplifications being the most frequent alteration, followed by rearrangements and mutations." (PMID 38255923, 2024). "Paradoxically, murine models of gastric cancer point to an improved immunotherapeutic effect of FGFR1 expression." (PMID 36966334, 2023). "MiR‐1205 directly targets FGFR1 to inhibit colony formation, metastasis, and resistance to cisplatin in gastric cancer cells, while circARVCF reverses this effect." (PMID 37750089, 2023). "Hub genes containing COL5A2, JAG1, TIMP1, FGFR1, PDFGA, VEGFA, and PTK2 were collected from the gene sets and were proven to be linked to the occurrence and development of gastric cancer." (PMID 35875363, 2022). "Collectively, these results suggested that Y14, as an effective inhibitor of FGFR1, synergistically enhanced the anti-cancer effect of 5-FU by inhibiting FGFR1 phosphorylation in two gastric cancer cell lines." (PMID 33041789, 2020). "It has been reported that high expression of FGFR1 was shown by 37% (40/109) in diffuse-type gastric cancer sample and 38% (38/100) in intestinal-type gastric cancer sample." (PMID 33041789, 2020). "In recent years, development of FGFR1 inhibitors targeting gastric cancer have attracted extensive attentions." (PMID 33041789, 2020). "It is also found that FGFR1 was significantly up-regulated in drug-resistant gastric cancer cell lines." (PMID 33041789, 2020). "Western blot analysis of the phosphorylated FGFR1 showed that Y14 inhibited the phosphorylation of FGFR1 in gastric cancer cells in a dose-dependent manner." (PMID 33041789, 2020). "Taken together, these results confirm that Y14 exerts anti-gastric cancer activity and enhances the sensitivity of gastric cancer cell to 5-FU by inhibiting the phosphorylation of FGFR1." (PMID 33041789, 2020).
gastric cancer (continued). "In recent years, the relationship between FGFR1 and gastric cancer has become increasingly apparent." (PMID 33041789, 2020). "Further, WB analysis revealed that the combination of 5-FU and Y14 significantly reduced FGFR1 phosphorylation in gastric cancer cells compared with those treated with 5-FU alone." (PMID 33041789, 2020). "Among them, compound Y14 was successfully screened out as a novel NDGA-based FGFR1 inhibitor with favorable anti-gastric cancer activity." (PMID 33041789, 2020). "By inhibiting FGFR1 phosphorylation and its downstream signaling pathway in gastric cancer cells, it inhibited the growth, migration, and survival of cancer cells, as well as enhancing the chemosensitivity of cancer cells to 5-FU." (PMID 33041789, 2020). "We also found that the expression of FGFR1 is significantly increased after 5-FU resistance in gastric cancer cells." (PMID 33041789, 2020). "This study provides a potential FGFR1 inhibitor for the treatment of gastric cancer and provides a reference for the discovery of novel FGFR1 inhibitors from the sources of bioactive natural products." (PMID 33041789, 2020). "Compared with the cells treated with 5-FU alone (4, 8, and 12 h), combined treatment with 5-FU and Y14 significantly down-regulated the level of FGFR1 phosphorylation in gastric cancer cells." (PMID 33041789, 2020). "We found that FGFR1 mRNA and protein levels were significantly up-regulated in all of the gastric cancer cell lines compared with normal GES-1 cells." (PMID 30484492, 2018). "Taken together, our results showed that miR-497 inhibited FGFR1 expression and consequently induced growth inhibition and apoptosis in gastric cancer cells." (PMID 30484492, 2018). "We also found that the expression levels of FGFR1 and miR-497 were inversely correlated in the 74 gastric cancer tissues (r=–0.577, P<0.001)." (PMID 30484492, 2018). "Fibroblast growth factor receptor 1 (FGFR1) has been reported in gastric cancer to be a prognostic factor." (PMID 30484492, 2018). "Another potent selective FGFR inhibitor is AZD4547, which has been tested in a phase II clinical trial for patients with advanced breast, lung and gastric cancer harboring FGFR1 or FGFR2 amplifications." (PMID 30181810, 2018). "In the present study, we aimed to evaluate the prognostic significance of FGFR1 in patients with gastric cancer, and the mechanism of miR-497-regulated FGFR1 in gastric cancer cell proliferation and apoptosis." (PMID 30484492, 2018). "As an oncogene, FGFR1 knockout mediated cell growth inhibition and apoptosis in gastric cancer cells." (PMID 30484492, 2018). "In gastric cancer, the expression of miR-133b was inversely correlated with that of FGFR1, bioinformatic analysis revealed FGFR1 was a direct of miR-133b, and by targeting FGFR1, miR-133b inhibited the growth of gastric cancer cells." (PMID 30574019, 2018). "The present study intended to revalidate the prognostic significance of FGFR1 in patients with gastric cancer, and the mechanism of miR-497-regulated FGFR1 was investigated in gastric cancer cell proliferation and apoptosis." (PMID 30484492, 2018). "Our study also found that FGFR1 was a direct target of miR-497, and we were the first to explore the functional roles of miR-497 and FGFR1 in gastric cancer cells proliferation and apoptosis." (PMID 30484492, 2018). "A previous study reported that FGFR1 was a direct target gene inhibited by miR-133b in gastric cancer." (PMID 30574019, 2018). "Emerging evidence has suggested that FGFR1 plays crucial roles in the pathological processes of gastric cancer, including cell proliferation, metastasis, recurrence, and poor prognosis." (PMID 30484492, 2018). "In our study, shRNA was designed to inhibit FGFR1 expression by post-transcriptional gene silencing to explore the functions of FGFR1 in gastric cancer cell proliferation and apoptosis." (PMID 30484492, 2018).
gastric cancer (continued). "Fibroblast growth factor receptor (FGFR) is one RTK, and we previously reported the clinical significance of FGFR1, 2, 3, and 4 in gastric cancer." (PMID 28056982, 2017). "Previous studies have indicated that miR-133b-regulated FGFR1-mediated tumor growth occurs in gastric cancer." (PMID 24816813, 2014). "Our data indicated that both FGFR1 and FGFR2 amplification were associated with poor survival in breast, lung, and gastric cancers." (PMID 25171497, 2014). "In addition, the expression of SFRPs was positively correlated with the expression of FGFR1, which was an independent prognostic factor in gastric cancer." (PMID 34205081, 2021). "Several reports have shown that FGFR1 mRNA and protein were highly expressed in cancer tissues of patients with gastric cancer and could result in distant metastasis and recurrent disease." (PMID 33041789, 2020). "Furthermore, compared with 5-FU treatment alone, the combination of Y14 and 5-FU significantly reduced the phosphorylation level of FGFR1, and enhanced the anti-cancer effect by inhibiting the viability and colony formation in two gastric cancer cell lines." (PMID 33041789, 2020). "It is reported that both mRNA and protein expression of FGFR1 are high in gastric cancer tissues." (PMID 33041789, 2020). "Encouraged by its promising FGFR1 inhibitory potency, we attempted to evaluate whether Y14 combined with 5-FU could enhance the sensitivity of gastric cancer cells to 5-FU." (PMID 33041789, 2020). "Moreover, some phase 1/II clinical trials have proved the safety and efficacy of targeted FGFR1 in the treatment of advanced gastric cancer (NCT01795768, NCT02257541)." (PMID 33041789, 2020). "Furthermore, the result of qRT-PCR showed that FGFR1 was significantly up-regulated in drug-resistant gastric cancer cell lines SGC-7901/VCR and SGC-7901/ADR, which is in accordance with the mRNA profiling results." (PMID 33041789, 2020). "In recent years, growing evidence indicates that FGFR1 might be a promising therapeutic target for the treatment of gastric cancer." (PMID 33041789, 2020). "This work also provides evidence that Y14, an effective FGFR1 inhibitor, could be used alone or in combination with chemotherapy to treat gastric cancer in the future." (PMID 33041789, 2020). "In addition, the mRNA levels of FGFR1 were significantly up-regulated in the gastric cancer tissues compared to the corresponding adjacent normal tissues." (PMID 30484492, 2018). "Therefore, we firmly believe that FGFR1 as an oncogene can serve as an independent prognostic factor and a very promising therapeutic target for patients with gastric cancer." (PMID 30484492, 2018). "Thus, we proposed the possibility that FGFR1 and miR-497 had exactly the opposite role in the progression and development of gastric cancer." (PMID 30484492, 2018). "Experimental validations delineated a novel regulatory mechanism that miR-497 could serve as tumor suppressor in the progression of gastric cancer by blocking FGFR1 expression." (PMID 30484492, 2018). "More importantly, miR-497 and FGFR1 might contribute to the development of prognostic indices and therapeutic targets for patients with gastric cancer." (PMID 30484492, 2018). "Several studies have reported that FGFR1 is overexpressed in gastric cancer tissues and may be considered as a prognostic factor." (PMID 30484492, 2018). "In addition, the expression of FGFR1 was up-regulated in gastric cancer cell lines compared to normal GES-1 cells." (PMID 30484492, 2018). "Based on these results, we hypothesized that FGFR1 may be an oncogene in the progression of gastric cancer." (PMID 30484492, 2018). "Additionally, high expression levels of FGFR1, FGFR2, or FGFR4 are associated with tumor progression and poor survival in patients with gastric cancer." (PMID 26993773, 2016). "Recently, miR-133b is found to negatively regulate FGFR1 in gastric cancer and might act as a tumor suppressor in GC." (PMID 25433493, 2014).
gastric cancer (continued). "The group with SOX2 suppression had higher rates of mutations in many gastric cancer-associated genes such as epigenetic modifiers ARID1A, KMT2D, KMT2C, and KMT2B, as well as higher rates of mutations in genes encoding for receptor tyrosine kinases ERBB4 and FGFR1." (PMID 40149431, 2025). "Aberrant fibroblast growth factor receptor-1 (FGFR1), a key driver promoting gastric cancer (GC) progression and chemo-resistance, has been increasingly recognized as a potential therapeutic target in GC." (PMID 33041789, 2020). "Furthermore, to investigate whether Y14 enhances the chemosensitivity of 5-FU to gastric cancer cells by inhibiting FGFR1, we detected the activation status of FGFR1 in gastric cancer cells after the combination of Y14 and 5-FU." (PMID 33041789, 2020). "Hence, next efforts were made to clarify whether Y14 can exert anti-gastric cancer effect and sensitize gastric cancer cells to chemotherapeutic drugs by inhibiting FGFR1." (PMID 33041789, 2020). "miR-497 targeted to inhibition of FGFR1 expression blocked gastric cancer cells proliferation and induced apoptosis, indicating that miR-497 and FGFR1 may serve as a potential therapeutic target for the treatment of gastric cancer." (PMID 30484492, 2018). "In a study conducted in China, 5557 Chinese patients with solid organ malignancies were evaluated for the presence of FGFR1-4 alterations via NGS, which included 254 cases of gastric cancers." (PMID 38255923, 2024). "For example, in a translational clinical trial, 12.5 and 33% of gastric cancers exhibiting FGFR1- and FGFR2-amplification, respectively, exhibited responses to the FGFR1-3 inhibitor AZD4547." (PMID 34344433, 2021). "Multiple oncogenic signaling pathways (gastrin-CREB, NGF-neurotrophin, PDGF, EGFR, ERK, ERBB4, FGFR1, RAS, VEGFR2 and RAF/MAP kinase) known to be active in aggressive gastric cancers were strikingly diminished in gastric cancers with low DOK6 expression." (PMID 29872697, 2017). "Amplification of seven oncogenes: HER2, EGFR, FGFR1, FGFR2, MET, KRAS and IGF1R has been identified in gastric cancer." (PMID 27437872, 2016). "A recent genomic study of gastric cancers identified somatic copy number alterations of seven oncogenes involved in tyrosine kinase/MAP-kinase pathways: KRAS, EGFR, HER2, FGFR1, FGFR2, MET and IGF1R." (PMID 27437872, 2016). "Recently, a phase II study was designed to assess the activity of the FGFR inhibitor AZD4547 in patients with FGFR1- and FGFR2-amplified breast, squamous lung, or stomach cancers, whose cancers had progressed following previous chemotherapy (NCT01795768)." (PMID 25171497, 2014). "Bioinformatic analysis of tissues from gastric cancer patients also revealed that the degree of infiltration of CD8+ and CD4+ T-cells, macrophages and DCs was positively correlated with the expression of FGFR1 in tumor cells." (PMID 36966334, 2023). "E7090 selectively inhibits FGFR1–3 and has been found to be effective in patients with cholangiocarcinoma with FGFR2 gene fusions and in patients with gastric cancer with FGFR2 gene amplification or increased expression, but more information is needed for a larger sample size." (PMID 37750089, 2023). "In several different cancers, TPR is present through fusion genes, which is formed by coiled-coil motif in TPR with some kinase partner genes such as MET (gastric cancer), NTRK1 (thyroid carcinoma), FGFR1 (myeloproliferative syndromes), and ALK (lung adenocarcinoma)." (PMID 34722501, 2021). "Although much progress has been made in this field, no FDA-approved drug is available to treat gastric cancer by inhibiting FGFR1." (PMID 33041789, 2020). "Next, pharmacological experiments showed that Y14 could significantly inhibit the phosphorylation of FGFR1 and its downstream kinase AKT and ERK, thus inhibiting the growth, survival, and migration of gastric cancer cells." (PMID 33041789, 2020).
gastric cancer (continued). "Besides, our group also discovered some favorable FGFR1 inhibitors L16H50, L6123, and Af23, which exhibited effective anti-gastric cancer effects in vitro." (PMID 33041789, 2020). "In our study, we found that FGFR1 was significantly increased in gastric cancer tissues compared to adjacent non-tumor tissues." (PMID 30484492, 2018). "A functional connection between the MET and FGFR1 pathways is supported by the finding that FGFR inhibitions sensitized MET-amplified gastric cancer cells to treatment with an anti-MET antibody and by the reactivation of MET that drove MAPK activity as a consequence of AR to the FGFR1 inhibitor." (PMID 30140389, 2018). "If these findings can be translated into gastric cancer settings, patients with high expression of MET, FGFR1 and ERBB2 may exhibit EGFR therapeutic resistance." (PMID 27738318, 2016). "However, the comparative analysis of the expression of FGFR1 in gastric cancer tissues and adjacent non-tumor tissues or normal cells and gastric cancer cell lines had not been presented in these studies." (PMID 30484492, 2018). "However, miR-497-targeted FGFR1 has not been explored in the carcinogenesis of gastric cancer." (PMID 30484492, 2018).